NIBAN2 (niban apoptosis regulator 2)
Description:
May play a role in apoptosis suppression. May promote melanoma cell invasion in vitro.
Synonyms: MINERVA; C9orf88; FAM129B; DKFZP434H0820; FLJ13518; FLJ22151; FLJ22298; bA356B19.6; MEG-3; OC58
Tractability: Antibody: its Gene Ontology location is reachable by antibodies, with high confidence; the Human Protein Atlas places it where antibodies can reach. PROTAC: ubiquitination databases record sites on it.
Gene: Protein-coding gene on chromosome 9 (127,505,339 to 127,578,989, reverse strand). Ensembl gene ENSG00000136830.
Subcellular location: Cytoplasm, cytosol; Cell junction, adherens junction; Membrane
Subcellular location (Human Protein Atlas): Cytosol; Plasma membrane; Nucleoplasm
Gene Ontology:
Molecular function: cadherin binding; protein binding; transcription coactivator activity
Biological process: gonadotropin secretion; negative regulation of apoptotic process; negative regulation of cell population proliferation; negative regulation of DNA biosynthetic process; negative regulation of DNA-templated transcription; positive regulation of DNA-templated transcription; positive regulation of transcription regulatory region DNA binding
Cellular component: adherens junction; cytoplasm; cytosol; extracellular exosome; nucleoplasm; nucleus; plasma membrane; membrane
Genetic constraint (gnomAD): Loss-of-function variants: 34 observed, 80.36 expected, observed/expected ratio (o/e) 0.42, 90% interval 0.32 to 0.56. The upper end of that interval is the gene's LOEUF score, 0.56, which puts it in group 2 of 6, group 1 being the genes least tolerant of losing a copy. Missense variants: 870 observed, 1,002.5 expected, observed/expected ratio (o/e) 0.87, 90% interval 0.82 to 0.92. Synonymous variants: 429 observed, 438.23 expected, observed/expected ratio (o/e) 0.98, 90% interval 0.9 to 1.06.
Homologues: Orthologues: chimpanzee NIBAN2 (99% identical), macaque NIBAN2 (97% identical), mouse Niban2 (90% identical), pig NIBAN2 (90% identical), dog NIBAN2 (90% identical), rat Niban2 (86% identical), rabbit NIBAN2 (85% identical), guinea pig NIBAN2 (84% identical), tropical clawed frog niban2 (58% identical), zebrafish niban2b (55% identical), zebrafish niban2a (54% identical). Paralogues in human: NIBAN1 (34% identical), NIBAN3 (21% identical).
Diseases named in the same sentence as NIBAN2 in open-access papers:
NIBAN2 is named in the same sentence as 26 diseases in open-access papers, as found by Europe PMC text mining. Sharing a sentence is not in itself a finding about the gene and the disease. The quoted sentences say what the papers report.
glioma (2 papers, 2025 to 2026). A benign or malignant brain and spinal cord tumor that arises from glial cells (astrocytes, oligodendrocytes, ependymal cells). "In this study, we identified that the NIBAN2 is highly expressed in glioma tissues and GSCs, and its expression is closely associated with poor patient prognosis." (PMID 41736673, 2026). "NIBAN2 levels were positively associated with tumor grade and inversely correlated with patient prognosis in glioma tissues." (PMID 40944417, 2025). "Niban‐like protein 2 (NIBAN2) has recently been linked to various neurological diseases; however, its exact role in glioma development remains unclear." (PMID 40944417, 2025). "Our results showed that NIBAN2 was specifically overexpressed in gliomas and its expression level closely correlated with prognosis." (PMID 40944417, 2025). "The research outcomes revealed that NIBAN2 was highly upregulated in gliomas and its levels were strongly correlated with tumor grade and clinical outcomes." (PMID 40944417, 2025). "Collectively, these results indicated that NIBAN2 triggered glioma progression by stimulating the JAK2/STAT3/c‐Myc signaling pathway." (PMID 40944417, 2025). "Functional assays showed that NIBAN2 enhanced glioma cell aggressiveness by activating JAK2/STAT3 signaling and promoted tumor growth by preventing apoptosis and accelerating the cell cycle." (PMID 40944417, 2025). "The findings of this study show that NIBAN2 plays a key role in glioma aggression and poor prognosis, suggesting that it is a potential therapeutic target." (PMID 40944417, 2025). "IHC analysis showed that the staining intensity of NIBAN2 varied significantly between glioma grades." (PMID 40944417, 2025). "Mechanistically, HIF‐1α targeted NIBAN2 to upregulate it, thereby promoting glioma progression by stimulating the JAK2/STAT3/c‐Myc signaling axis." (PMID 40944417, 2025). "Functional assays, such as CCK‐8, colony formation, EdU, and transwell assays, demonstrated that NIBAN2 knockdown significantly decreased glioma cell aggressiveness, indicating that NIBAN2 plays a key role in these processes." (PMID 40944417, 2025). "Flow cytometry showed that NIBAN2 knockdown triggered apoptosis and hindered cell cycle progression in glioma cells." (PMID 40944417, 2025). "Transwell assays showed that the overexpression of NIBAN2 significantly increased glioma cell invasion and migration, suggesting that NIBAN2 enhances these malignant tumor characteristics." (PMID 40944417, 2025). "Consistent with the in vitro findings, in mice with intracranial orthotopic glioma transplantation, c‐Myc silencing significantly decreased the increase in cell growth resulting from NIBAN2 upregulation." (PMID 40944417, 2025). "NIBAN2 concentrations in normal human astrocytes (NHAs) and eight glioma cell lines (U‐251, T98G, LN‐229, A‐172, LN‐18, H4, U118MG, and U‐87MG) were quantified by WB." (PMID 40944417, 2025). "This emphasizes the potential of NIBAN2 as a therapeutic target for glioma and suggests that further studies are necessary to elucidate its specific molecular mechanisms and evaluate its therapeutic relevance." (PMID 40944417, 2025). "In U‐87MG and LN‐229 cell lines, shRNAs targeting c‐Myc were used to explore its function in NIBAN2‐driven glioma cell growth." (PMID 40944417, 2025). "Quantitative reverse transcription–polymerase chain reaction, western blotting, and immunohistochemistry were used to evaluate NIBAN2 expression in glioma tissues." (PMID 40944417, 2025). "The glioma tissues showed increased NIBAN2 levels compared to the NBTs." (PMID 40944417, 2025). "NIBAN2 was significantly overexpressed in gliomas versus NBTs." (PMID 40944417, 2025). "The glioma cell lines exhibited elevated NIBAN2 protein levels compared to NHAs." (PMID 40944417, 2025). "Moreover, there was a positive relationship between a higher glioma grade and increased expression levels of NIBAN2 at both the RNA and protein levels." (PMID 40944417, 2025).
glioma (continued). "In addition, we examined the effects of NIBAN2 on glioma progression in various functional trials." (PMID 40944417, 2025). "Therefore, our objectives were to investigate the function of NIBAN2 in glioma, identify novel mechanisms that may facilitate glioma progression, and propose potential targets for future therapeutic interventions." (PMID 40944417, 2025). "NIBAN2 may promote glioma growth by activating the JAK2/STAT3 signaling pathway." (PMID 40944417, 2025). "It is highly activated in gliomas (especially GBM) and promotes tumor progression, treatment tolerance, and immune escape, but it is unclear whether NIBAN2 mediates its activation." (PMID 40944417, 2025). "However, no studies have focused on the function of NIBAN2 in the pathogenesis of glioma." (PMID 40944417, 2025).
brain tumors (1 paper, 2025). "IF for Ki‐67 in brain tumors revealed that NIBAN2 suppression decreased Ki‐67 levels compared to their levels in controls." (PMID 40944417, 2025).
glioblastoma (1 paper, 2026). The most malignant astrocytic tumor (WHO grade IV). "Clinical samples further confirmed the co-upregulation of NIBAN2, FLII, and RREB1 in GBM (Glioblastoma) tissues, which correlates with SOX2 and Ki-67 expression and poor prognosis." (PMID 41736673, 2026).
liver cancer (1 paper, 2025). An epithelial or non-epithelial malignant neoplasm that arises from the liver. "For example, some studies have found that NIBAN2 shows different expression patterns in gastric and liver cancers, which may be closely associated with tumor progression." (PMID 40944417, 2025).
osteoporosis (1 paper, 2025). A condition of reduced bone mass, with decreased cortical thickness and a decrease in the number and size of the trabeculae of cancellous bone (but normal chemical composition), resulting in increased fracture incidence. "Through integral analyses of multiple datasets, NIBAN2 is found to be tightly associated with bone formation and osteoporosis." (PMID 40051391, 2025). "In summary, Niban2 overexpression regulates Runx2 AS and rescues bone loss in OBs during osteoporosis in vivo." (PMID 40051391, 2025). "NIBAN2 promoted OB differentiation and rescued bone loss in an osteoporosis mouse model." (PMID 40051391, 2025). "Furthermore, NIBAN2 downregulation was tightly associated with osteoporosis, and NIBAN2 overexpression rescued bone loss in OVX‐induced osteoporosis." (PMID 40051391, 2025). "We found that NIBAN2 was tightly associated with OB differentiation and osteoporosis." (PMID 40051391, 2025). "Niban2 displayed highest expression level in Bglap+ cells and decreased in all above cell types during senile osteoporosis in single cell level and biological replicates." (PMID 40051391, 2025). "Most importantly, NIBAN2 expression level negatively correlates with RUNX2 spliced isoforms and bone loss in osteoporosis patients." (PMID 40051391, 2025). "The NIBAN2 expression level was positively correlated with the RUNX2 exon 6‐inclusive ratio in osteoporosis patients." (PMID 40051391, 2025). "Most importantly, NIBAN2 correlation to RUNX2 alternative splicing and bone loss was verified in osteoporosis patients." (PMID 40051391, 2025). "To further confirm the correlation between NIBAN2 and osteoporosis, we performed multiplex immunofluorescence (mIF) to explore its expression in different OB stages and senile osteoporosis mouse model." (PMID 40051391, 2025). "Our study reveals a novel function of NIBAN2 in OB differentiation and osteoporosis." (PMID 40051391, 2025). "Our study suggests that NIBAN2 may be a potential target for anabolic therapy of osteoporosis." (PMID 40051391, 2025). "Thus, this research identifies NIBAN2‐regulated RUNX2 alternative splicing as a potential mechanism of osteoblast differentiation that may present strategies for antagonizing osteoporosis." (PMID 40051391, 2025). "Thus, our research identifies NIBAN2‐regulated RUNX2 alternative splicing as a potential mechanism of osteoblast differentiation that may present strategies for antagonizing osteoporosis." (PMID 40051391, 2025). "To address the clinical relevance of our findings, we collected bone tissues from osteoporosis patients and non‐osteoporosis control and measured RUNX2 alternative splicing and the expression level of NIBAN2." (PMID 40051391, 2025).
postmenopausal osteoporosis (1 paper, 2025). Metabolic disorder associated with fractures of the femoral neck, vertebrae, and distal forearm. "NIBAN2 rescued bone loss in postmenopausal osteoporosis model." (PMID 40051391, 2025).
cancer (7 papers, 2017 to 2025). A tumor composed of atypical neoplastic, often pleomorphic cells that invade other tissues. "In some types of cancer, the expression of NIBAN2 may be associated with tumor invasiveness and metastasis." (PMID 40944417, 2025). "Screening for possible signaling pathways using the Cignal Finder Cancer 10‐Pathway Reporter Array demonstrated that the JAK/STAT signaling axis was markedly downregulated after NIBAN2 knockdown in U‐87MG and LN‐229 cells." (PMID 40944417, 2025). "Pan‐Cancer Database analysis also showed that NIBAN2 was significantly overexpressed in most tumors." (PMID 40944417, 2025). "ALA reduces the phosphorylation of ERK1/2 and its effectors, NIBAN2 and Stathmin 1, highlighting its potential as a therapeutic target in cancer treatment." (PMID 40868211, 2025).
tumor (3 papers, 2013 to 2025). "Overall, NIBAN2 overexpression reduced cell death and accelerated tumor progression, both in vitro and in vivo." (PMID 40944417, 2025). "To better understand the effect of NIBAN2 on tumor cell growth, we conducted CCK‐8, colony formation, TUNEL, and EdU assays." (PMID 40944417, 2025). "Further investigations revealed that NIBAN2 may be an important regulatory factor in the tumor microenvironment by affecting cell proliferation, migration, and immune escape mechanisms." (PMID 40944417, 2025). "The results showed that NIBAN2 overexpression increased tumor cell growth." (PMID 40944417, 2025). "Additionally, NIBAN2 overexpression promoted tumor growth in vivo, with Ki‐67 IF staining showing a higher proliferation index in the NIBAN2‐overexpression group than the control group." (PMID 40944417, 2025). "NIBAN2 may affect tumor behavior by controlling the aggressiveness of tumor cells." (PMID 40944417, 2025). "Moreover, to confirm the function of NIBAN2 in triggering tumor growth via activation of the JAK/STAT pathway, NIBAN2 was suppressed and upregulated in U‐87MG and LN‐229 cells, respectively." (PMID 40944417, 2025).
neurodegenerative disease (1 paper, 2025). A disorder of the central nervous system characterized by gradual and progressive loss of neural tissue and neurologic function. "Additionally, the expression of NIBAN2 in the nervous system has garnered interest, particularly in neurodegenerative diseases." (PMID 40944417, 2025).
NIBAN2 also shares sentences with these, for which no sentence is quoted: melanoma (7 papers); breast carcinoma (2); diabetic nephropathy (2); age (1); asthma (1); breast tumor (1); cardiomyopathy (1); cleidocranial dysplasia (1); colorectal cancer (1); Hyperglycemia (1); Jaundice (1); lung carcinoma (1); lymphoma (1); metastatic melanoma (1); neurological diseases (1); non-small cell lung carcinoma (1); prostate carcinoma (1).